CDH1 (cadherin 1)
Diseases named in the same sentence as CDH1 in open-access papers (continued):
Sharing a sentence is not in itself a finding about the gene and the disease.
tumor (continued). "Consistently, decreased expression of Cdh1 depends on cadherin switching, a process closely associated with tumor invasion and metastasis, two common characteristics of advanced cancers." (PMID 37305018, 2022). "Lobular BC is a distinct tumor entity characterized by a special histomorphology, distinct genetic alterations, including CDH1 mutation, and comparatively slow, estrogen-dependent growth." (PMID 35842479, 2022). "In patients with invasive ductal BCs, decreased levels of E-cadherin encoding gene CDH1 were found in tumor samples compared to healthy breast tissues, but CDH1 expression increased in LNMs compared to BC samples." (PMID 36292996, 2022). "Early studies suggest that CDH1, as a tumor suppressor gene, as evidenced by mutations or methylation of CDH1, silences CDH1 expression, thus increasing the incidence of BC, as well as infiltrative tumor growth and metastasis." (PMID 35784532, 2022). "CDH1 is a tumour suppressor, and the vast majority of variants detected here were LOF (128 of 141, 90.8%, 95% CI = 84.9–94.5%), and distributed throughout the coding sequence." (PMID 34949788, 2022). "CDH1 encodes for E-cadherin, a homophilic transmembrane protein with a tumor suppressor function that is localized to the adherens junctions in epithelial tissue." (PMID 35887173, 2022). "Invasive lobular breast cancers (ILCs) are histologically classified by their discohesive growth pattern, due to loss of the cell adhesion glycoprotein E-cadherin (CDH1), which arises via mutation in CDH1 in around half of these tumours." (PMID 35053458, 2022). "Several sets, including those for cell migration, ZEB1 targets, EGFR signaling, lin genes silenced by the tumor microenvironment, and CDH1 targets, were all closely linked to cancer." (PMID 35645615, 2022). "Cases displaying high ITGB1/low CDH1 expression were strongly associated with diffuse type gastric cancer and increased tumour grade." (PMID 34486077, 2022). "We also examine germline cancer-risk variants by ethnicity across several tumour subtypes and identify, for the first time, CDH1 variant enrichment in individuals with CRC and colorectal signet-ring cell cancer (CSRCC)." (PMID 34949788, 2022). "Tumor-derived mutations, for instance, mutations of CDH1 and CTNNA1 which are commonly detected in hereditary diffuse GC, are detected by next-generation sequencing." (PMID 36302755, 2022). "CDH1 mutant tumours also exhibited a higher mutation burden as well as increased presence of APOBEC-dependent mutational signatures 2 and 13 compared to CDH1 wild-type tumours." (PMID 35053458, 2022). "Inactivating mutation of CDH1 (chromosome 16), encoding for E-cadherin, are known to contribute to malignant cell detachment from the primary tumor." (PMID 34202213, 2021). "CDH1-deficient cells proliferate inefficiently and CDH1 heterozygous animals show increased susceptibility to spontaneous tumors, largely conferring CDH1 a tumor suppressor role." (PMID 33130827, 2021). "For example, loss of CDH1 (E-cadherin) expression in CRC is associated with infiltrative tumor growth pattern and lymph node metastasis." (PMID 34214117, 2021). "CDH1, a tumor suppressor gene encoding E-cadherin, plays a crucial role in maintaining intercellular junctions in the epithelium." (PMID 34827193, 2021). "Although a loss of function or downregulation of CDH1 has been associated with primary cancer and metastases, it has also been found that CDH1 can be a trigger of tumor aggressiveness and metastases through the reversion of EMT to MET process." (PMID 34768995, 2021). "CDH1 is a tumor suppressor gene encoding the transmembrane protein E-cadherin, which is primarily localized to the epithelial basolateral membrane, and constitutes a critical component of adherens junctions." (PMID 35008266, 2021).
tumor (continued). "PGK1 expression was lower in tumor specimens containing somatic mutations of CDH1 (mutation prevalence 14.1%)." (PMID 34291087, 2021). "One analysis looking at the downstream effect of TCF12 alterations showed a downregulation of TCF21, EZH2, and BMI1 pathway and especially CDH1 (E-cadherin), which has been shown to be implicated in tumor characteristics and metastasis." (PMID 34675774, 2021). "During EMT, HMGA2 promotes the binding of the de novo DNA methyltransferase 3A (DNMT3A) to the Cdh1 promoter, inducing the hypermethylation and silencing of the tumor-suppressor E-Cadherin (CDH1); this causes tumor cell invasion." (PMID 34439740, 2021). "There is a striking similarity in the genomic profiles of CLCIS, PLCIS, and FLCIS (and invasive tumours), with recurrent gains of 1q and losses on 16q and CDH1 mutations suggesting they arise from a common aetiology." (PMID 33413533, 2021). "ILC has also been one of the first tumor types associated with a specific tumor suppressor gene, namely, CDH1/E-cadherin." (PMID 34359596, 2021). "CDH1 is a tumor suppressor and cell polarity regulator and the loss of CDH1 promotes motility and invasion." (PMID 34445100, 2021). "The role of CDH1 in OD risk identified here is corroborated by our finding that rare non-silent CDH1 variants predicted to be deleterious were also observed in tumor DNA of 6% of ODs, WHO grade II/III." (PMID 33929593, 2021). "E-cadherin encoded by human CDH1 gene plays important roles in tumorigenesis as well as in tumor progression, invasion and metastasis." (PMID 34422902, 2021). "Case 10S was extremely instable with an instability index of 68.8 yet maintaining a gain of CCND1 accompanied by a loss of CDH1 in essentially all cells of the tumor." (PMID 34282768, 2021). "Herein, by following families and individuals carrying the CDH1 c.1901C>T variant, we characterized the first CDH1-related founder effect in Northern Portugal, traced its origin, and portraited tumour spectrum and age of onset in carrying families." (PMID 34503274, 2021). "The CDH1 gene encodes the cell–cell adhesion protein E-cadherin, the intracellular domain of which binds several catenins, such as β-catenin, and acts as a tumor suppressor." (PMID 33929593, 2021). "One of the most important players in carcinogenesis of both hereditary and sporadic GC is the CDH1 gene, encoding E-cadherin, a component of the adherent junctions between epithelial cells with a tumor suppressor activity." (PMID 34066170, 2021). "As reduced CDH1 expression was associated with tumor size, lymph node status, and TNM stage, we subsequently investigated if CDH1 histological score (H score) was associated with any other clinical parameters." (PMID 32665033, 2020). "In cancer literature, the role of E-cadherin, encoded by Cdh1 gene, that functions as a tumor suppressor is widely reported." (PMID 32015681, 2020). "This cassette includes CDH1, itself a major tumor suppressor gene that encodes E-cadherin, an established modulator of the Hippo pathway." (PMID 32641858, 2020). "CDH1 mutations were also observed significantly more frequently in tumours with signet ring cells (p = 0.043)." (PMID 31949278, 2020). "CDH1 is a tumor suppressor gene encoding E-cadherin, which is essential for cellular adhesion and tissue morphogenesis." (PMID 32605217, 2020). "In fact, detection of identical CDH1/E-cadherin mutations and matching CNAs in tumor cells microdissected from regions with pure conventional ILBC growth pattern and almost pure tubular elements proved clonal relatedness." (PMID 32572153, 2020).
tumor (continued). "For instance, genetic loss or epigenetic silencing of E‐cadherin (CDH1), which has been shown as a tumor suppressor, was frequently detected in cancers." (PMID 32979859, 2020). "According to previous reports, G9a activity increases, causing an increase in global histone methylation, and further cause transcriptional repression of different tumor suppressors, including CDH1, DUSP5, SPRY4, and RUNX3." (PMID 32015216, 2020). "Tumor tissue from these regions was purified by microdissection and was subjected to CDH1 mutational analysis." (PMID 32572153, 2020). "As expected, somatic CDH1 mutations were positively correlated with distant metastases (p = 0.019) and tumours with signet ring cells (p = 0.043)." (PMID 31949278, 2020). "CDH1, also belonging to the cadherin family, encodes E-cadherin, which has been reported to have a tumor suppressor role, acting not only as an adhesive protein, but also as crucial in growth development and carcinogenesis." (PMID 32276436, 2020). "A similar observation can be made with the downregulation of hsa-miRNA-203 (hsa-miRNA-203a or hsa-miRNA-203b), which was associated with VIM and SNAI1 upregulation and CDH1 downregulation in NSCLC tumor tissues." (PMID 32438606, 2020). "CDH1 is a tumour suppressor gene that encodes E-cadherin, a homophilic cell-to-cell adhesion protein that is localised to the adherens junction on the basolateral surface of epithelial cells." (PMID 30066183, 2019). "The analysis by qRT-PCR of the E-cadherin encoding gene (Cdh1) confirmed its enhanced expression in tumor xenografts derived from PATZ1-expressing cells compared to controls." (PMID 30744101, 2019). "Consistent with the metagene selection method, hierarchical clustering of gene expression data from each of these pathways showed variably sized clusters of genes with either strikingly high or low expression in CDH1-deficient tumours." (PMID 30066183, 2019). "E-cadherin is a 120 kDa transmembrane glycoprotein encoded by the CDH1/E-cadherin gene located on chromosome 16q22.1, and it is considered a tumor suppressor gene due to its ability to negatively regulate cell proliferation." (PMID 31256188, 2019). "AKT is postulated to contribute to gastric carcinogenesis and to influence prognosis, and our bioinformatic analysis of the TCGA dataset showed that there was significant upregulation of AKT3 RNA in CDH1-deficient tumours, but variable AKT1 expression." (PMID 31540244, 2019). "The genes in the hierarchical clustering regions with the highest relative expression in CDH1-deficient tumours contained 92 known receptors or enzymes (excluding orphan GPCRs)." (PMID 30066183, 2019). "We searched for mutations in the CDH1 gene in tumor DNA from DGC (n = 13) and MGC (n = 7) patients by next generation sequencing (NGS)." (PMID 30642281, 2019). "The ZEB2 is one of the transcription factors associated with transcriptional repression of CDH1 in neoplastic diseases." (PMID 30645591, 2019). "Molecular analysis performed on the index tumor demonstrated a deleterious mutation in CDH1 exon 12 leading to early truncation of the CDH1 protein in the index tumor sample which was absent from the adjacent benign tissue." (PMID 31638990, 2019). "CDH1, encoding the cell–cell adhesion protein E-cadherin, is a tumour suppressor gene that is frequently mutated in sporadic diffuse-type gastric cancer (DGC), lobular breast cancer in situ (LCIS), and invasive lobular breast cancer (LBC)." (PMID 31540244, 2019). "Molecular interrogation confirmed a mutation in CDH1 exon 12 leading to early truncation of the CDH1 protein in the tumor cells." (PMID 31638990, 2019).
tumor (continued). "Total EMT (loss of CDH1 expression associated with overexpression of CDH2) was observed in only one tumor in the present study." (PMID 29845746, 2018). "Two of the three tumors harbored gene amplifications in the 10q26.1 locus, whereas the third tumor contained CDH1 mutations." (PMID 30361512, 2018). "This clue indicates that CDH1 mutation influences not only the tumor cells, but also the tumor microenvironment." (PMID 29520031, 2018). "This was associated with a decrease in invasion-associated genes (e.g., Fibronectin, VCAM1, Thrombospondin, MMP1) and an increase in CDH1/E-cadherin, previously associated with decreased tumor aggression." (PMID 29735912, 2018). "According to the results of somatic variants, the Q1334del/dup (n=23/52) in ARID1A and L15del (n=6/13) in CDH1 were detected at a frequency of 5∼33% of altered alleles in tumor tissue." (PMID 29050249, 2017). "The GS tumours, nearly diploid tumours, are correlated to diffuse histological variant and alterations of genes CDH1 and RHOA." (PMID 29094049, 2017). "For CDH1, the prevalence across all tumor sites of primary carcinomas having at least one mutation was 4.1%." (PMID 29156750, 2017). "Hypermethylation of host cell tumor suppressor genes including E-cadherin (CDH1), Cell Adhesion Molecule 1 (CADM1) and Death-Associated Protein Kinase 1 (DAPK1) was reported in recent studies." (PMID 28881717, 2017). "Evidence for E-cadherin’s role as a tumor suppressor has accumulated, with downregulation of CDH1 being linked with epithelial tumor progression, although its reexpression in tumors is reported to promote metastasis in later stages of tumor progression." (PMID 28750639, 2017). "The transition from the active to the inactive state of the CDH1 promoter is associated both in cell lines and human tumours with changes in the relative abundance of S and AS-paRNAs." (PMID 28555645, 2017). "Tumor cells exhibiting CDH1 malfunction and subsequently loss of intercellular adhesions tend to invade adjacent tissues and are considered as more aggressive compared to tumor cells of the intestinal type." (PMID 28427431, 2017). "Epithelial cadherin (E-cadherin, Cdh1) is the key molecule of adherens junctions and is implicated in the establishment of intercellular adhesion and tumor suppression of human epithelia." (PMID 27274359, 2016). "The main finding of this study is the association of CDH1 functional SNPs with overall survival in BC, particularly in patients with a more aggressive tumor at onset or with recurrent metastatic BC." (PMID 27852262, 2016). "Loss of CDH1 expression, a gene encoding E-cadherin, is related to tumor invasiveness, metastasis, and poor prognosis in ESCC." (PMID 27110300, 2016). "A comprehensive search using the keywords “CDH1,” “E-Cadherin,” “polymorphism,” “SNP,” and “variant” combined with “breast,” “cancer,” “tumor,” or “carcinomas” was conducted." (PMID 27349965, 2016). "E-cadherin (CDH1), located on chromosome 16q22.1, is one of the most important tumor suppressor genes encoding an adhesion glycoprotein." (PMID 27349965, 2016). "Among these is loss of adhesion between tumor cells caused by downregulation of CDH1 (also called E-cadherin) in response to genetic or epigenetic changes." (PMID 26918727, 2016). "CDH1 promoter hypermethylation is the most frequent second-hit inactivation mechanism in HDGC primary tumours, whereas a second mutation or deletion (LOH/intragenic deletions) is less frequently identified." (PMID 27514667, 2016). "For example, CDH1, the gene encoding epithelial cadherin (E-cadherin), is a tumor suppressor gene located on chromosome 16q22.1." (PMID 27464701, 2016). "Further, activation of WNT-signaling and loss of E-Cadherin (CDH1) contributes to dissociative growth of tumor budding cells and loss of an epithelial phenotype." (PMID 25884643, 2015).
tumor (continued). "The current understanding of the EMT process is that transcription factors including SNAI1, SNAI2, ZEB1, ZEB2 and TWIST1 down-regulate CDH1 expression which subsequently results in the loss of cell adhesion and migration of tumor cells." (PMID 26214683, 2015). "CDH1 gene is responsible for cell adhesion, promotes metastasis when mutated, and shows promoter methylation in up to 85% of tumours." (PMID 25889859, 2015). "CDH1 is a tumor suppressor gene that encodes E-cadherin and is known to be associated with various malignancies." (PMID 26429873, 2015). "This latter figure is supported by an independent exome sequencing study of ER-positive tumours in the clinical context of aromatase inhibitor response, where they identified CDH1 mutation in 20 out of 40 ILCs." (PMID 25849106, 2015). "Epithelial-cadherin is a cell-cell adhesion glycoprotein encoded by the CDH1 gene in humans, which has been characterized as a tumor suppressor." (PMID 26301412, 2015). "EMT type 3 is characterised by both loss of E-cadherin (cdh1) and invasive properties at the invasive front of the tumour." (PMID 26528548, 2015). "CDH1 loss has been frequently reported in OSCC particularly at the invasive tumor front, and is well-recognized as one of the hallmarks of EMT." (PMID 26214683, 2015). "The tumor was positive for two intronic variants in CDH1 both of which are expected to be benign (NM_004360.3:c.688−83G>A and c.2439+52G>A)." (PMID 25340522, 2014). "This ILC adhesion defect is constitutive, often reflecting frameshift mutations of the CDH1 gatekeeper tumor suppressor gene that cause truncation of the E-cadherin extracellular domain, together with loss of heterozygosity for the wild-type allele." (PMID 25385074, 2014). "CTNNB1 (β-catenin gene) and CDH1 (E-cadherin gene) are crucial components of cell-cell adhesion complexes and their loss has been associated with tumor metastasis and poor clinical outcome." (PMID 24971456, 2014). "As HDGC is an infiltrative tumor, endoscopy and biopsy-based diagnostic strategies are inefficient; furthermore, given the high penetrance of CDH1 mutations, prophylactic gastrectomy is recommended for affected patients." (PMID 25180051, 2014). "The CDH1 tumor suppressor gene encodes E-cadherin, a transmembrane glycoprotein that mediates calcium-dependent cell-cell adhesion." (PMID 25315765, 2014). "The EC gene, CDH1 present on chromosome 16q22.1.2, is a classic tumor suppressor gene and loss of EC results in dedifferentiation and invasion in carcinoma." (PMID 24634677, 2014). "CDH1 is widely considered to be an ‘invasion suppressor gene’ whose inactivation is associated with tumor progression." (PMID 25079037, 2014). "Loss of CDH1 expression is associated with poor prognosis in cancer patients and is considered to be a tumor suppressor." (PMID 24454732, 2014). "Epigenetic silencing of the E-cadherin gene CDH1 through DNA methylation and recruitment of HDACs to its promoter have been previously linked to metastasis and tumor progression." (PMID 24962136, 2014). "The connection between loss of E-cadherin and tumor progression has been well established, and studies have highlighted the epigenetic regulation of the CDH1 gene encoding E-cadherin to be instrumental for cancer cell metastasis." (PMID 24840099, 2014). "The CDH1 gene, located on the 16q22.1 chromosome, encodes the E-cadherin intercellular adhesion protein; this protein acts as a tumor suppressor and plays an important role in maintenance of the epithelial tissue architecture." (PMID 25180051, 2014).